RNY3P2 (RNY3 pseudogene 2)
Gene: Miscellaneous RNA gene on chromosome 13 (49,095,391 to 49,095,492, forward strand). Ensembl gene ENSG00000199788.
Homologues: Orthologues: chimpanzee Y_RNA (95% identical), macaque Y_RNA (95% identical). Paralogues in human: Y_RNA (89% identical), RNY3 (87% identical), Y_RNA (87% identical), RNY3P1 (86% identical), Y_RNA (86% identical), Y_RNA (85% identical), Y_RNA (84% identical), RNY3P4 (83% identical), Y_RNA (83% identical), RNY3P14 (82% identical), RNY3P9 (82% identical), Y_RNA (82% identical), and 94 more.